STK26 (serine/threonine kinase 26)
Description:
Serine/threonine-protein kinase that acts as a mediator of cell growth. Modulates apoptosis. In association with STK24 negatively regulates Golgi reorientation in polarized cell migration upon RHO activation. Phosphorylates ATG4B at 'Ser-383', thereby increasing autophagic flux. Part of the striatin-interacting phosphatase and kinase (STRIPAK) complexes. STRIPAK complexes have critical roles in protein (de)phosphorylation and are regulators of multiple signaling pathways including Hippo, MAPK, nuclear receptor and cytoskeleton remodeling. Different types of STRIPAK complexes are involved in a variety of biological processes such as cell growth, differentiation, apoptosis, metabolism and immune regulation.
Synonyms: MASK; MST4
Tractability: Small molecule: a structure with a bound ligand is known; a high-quality ligand is known; it has a high-quality binding pocket; it belongs to a druggable protein family. PROTAC: ubiquitination databases record sites on it; a small molecule that binds it is known.
Target class: STE protein kinase group; STE protein kinase STE20 family; STE protein kinase YSK subfamily; Protein Kinase; Kinase; Enzyme
Chemical probes: JA310 (high quality), MR24 (high quality)
Safety:
Unwanted effects reported when the protein is acted on. In parentheses: how it was acted on, where the effect was seen, and who reports it.
cardiac arrhythmia (cardiovascular system; source: Lamore et al. (2017))
Gene: Protein-coding gene on chromosome X (132,023,226 to 132,075,948, forward strand). Ensembl gene ENSG00000134602.
Subcellular location: Cytoplasm; Golgi apparatus
Subcellular location (Human Protein Atlas): Nucleoplasm; Centrosome; Cytosol; Golgi apparatus
Pathways (Reactome):
Programmed Cell Death: Apoptotic cleavage of cellular proteins
Gene Ontology:
Molecular function: ATP binding; identical protein binding; magnesium ion binding; protein binding; protein homodimerization activity; protein kinase activity; protein serine kinase activity; protein serine/threonine kinase activity
Biological process: cellular response to oxidative stress; cellular response to starvation; intracellular signal transduction; negative regulation of cell migration; positive regulation of microvillus assembly; protein autophosphorylation; protein phosphorylation; regulation of apoptotic process; regulation of plasma membrane bounded cell projection organization
Cellular component: apical plasma membrane; cell periphery; cytoplasm; cytosol; extracellular exosome; FAR/SIN/STRIPAK complex; Golgi apparatus; Golgi-associated vesicle; membrane; perinuclear region of cytoplasm; vesicle membrane
Homologues: Orthologues: chimpanzee STK26 (100% identical), macaque STK26 (99% identical), rabbit STK26 (99% identical), rat Stk26 (99% identical), mouse Stk26 (98% identical), dog STK26 (96% identical), pig STK26 (96% identical), guinea pig STK26 (93% identical), tropical clawed frog stk26 (88% identical), zebrafish stk26 (78% identical). Paralogues in human: STK24 (73% identical), STK25 (69% identical), MAP4K4 (41% identical), MINK1 (41% identical), TNIK (40% identical), TAOK1 (38% identical), STK39 (38% identical), TAOK3 (37% identical), STK3 (37% identical), STK4 (37% identical), OXSR1 (37% identical), MAP4K3 (36% identical), and 23 more.
Diseases named in the same sentence as STK26 in open-access papers:
STK26 is named in the same sentence as 54 diseases in open-access papers, as found by Europe PMC text mining. Sharing a sentence is not in itself a finding about the gene and the disease. The quoted sentences say what the papers report.
breast carcinoma (8 papers, 2015 to 2022). "Therefore, STK26 might play a role as a tumor suppressor gene in breast cancer." (PMID 31557882, 2019).
prostate carcinoma (8 papers, 2010 to 2025). A carcinoma that arises from epithelial cells of the prostate gland. "Subsequent studies showed that STK26 was a cancer-promoting gene in prostate cancer, liver cancer, and glioblastoma." (PMID 31557882, 2019).
glioblastoma (7 papers, 2019 to 2025). The most malignant astrocytic tumor (WHO grade IV). "In addition, the inhibition of STK26 suppressed autophagy and the tumorigenicity of glioblastoma cells, while its therapeutic targeting enhanced the antitumor effects of radiotherapy." (PMID 31557882, 2019).
glioma (4 papers, 2021 to 2025). A benign or malignant brain and spinal cord tumor that arises from glial cells (astrocytes, oligodendrocytes, ependymal cells). "Additionally, the mRNA expression levels of MST4/STK26, USP14, and ALKBH5 were positively correlated with ALKBH5 target genes, including FANCD2, FANCI, MKI67, and RAD51 within the TCGA and CGGA glioma datasets." (PMID 39990235, 2025).
melanoma (4 papers, 2019 to 2021). A malignant, usually aggressive tumor composed of atypical, neoplastic melanocytes. "Our results indicated that STK26 was downregulated in SCM compared to nevus, and its low expression was associated with poor prognosis of primary melanoma." (PMID 31557882, 2019). "Among these kinases, 6 (RPS6KB2, DSTYK, TBRG4, CDK4, POLR2E, FASTKD5) and 4 (STK26, PAK1, EPHB2 and JAK3) were consistently up- or down-regulated, respectively, in the metastatic lines of at least two pairs of melanoma cells." (PMID 32051510, 2020). "Our results showed that, similarly to STK26 and KCNT2, the transcription of CASP12 in melanoma was reduced relative to nevus, which might mediate the process of the conversion of nevus to melanoma." (PMID 31557882, 2019). "In addition, gray-scale analysis revealed statistically significant differences in the protein expression of STK26 (P = 0.0024) and KCNT2 (P < 0.0001) between normal skin and melanoma." (PMID 31557882, 2019).
colorectal cancer (3 papers, 2021 to 2025). A primary or metastatic malignant neoplasm that affects the colon or rectum. "To elucidate the specific mechanisms by which STK26 regulates the development of colorectal cancer, we performed eukaryotic transcriptome sequencing in wild-type and STK26-deficient SW480 cells." (PMID 40869379, 2025). "STK26 is highly expressed in colorectal cancer (CRC) and linked to tumorigenesis." (PMID 40869379, 2025). "Critically, the higher mRNA expression of STK26 correlated with worse disease-free survival in colorectal cancer patients." (PMID 40869379, 2025). "STK26 is highly expressed in colorectal cancer and correlates with poor prognosis and survival rate in colorectal cancer patients." (PMID 40869379, 2025). "In summary, we found a new mechanism of the 50 kDa ATF6 (p50), regulated by STK26, in the development and progression of colorectal cancer." (PMID 40869379, 2025). "In brief, these data indicate that the depletion of STK26 suppresses the growth, proliferation, and migration of colorectal cancer cells." (PMID 40869379, 2025). "Additionally, the transwell migration assay demonstrated a similar result in that the overexpression of STK26 markedly enhanced the migration ability of colorectal cancer cells." (PMID 40869379, 2025). "Then, to assess whether STK26 is aberrantly overexpressed in colorectal cancer, the GEPIA 2 online tool was used." (PMID 40869379, 2025). "Genetic tracing of MST4‐expressing cell lineage via Stk26‐Cre;R26‐tdTomato mice suggest a subpopulation of ISCs with high levels of MST4 might develop into colorectal cancer stem cells." (PMID 34240584, 2021). "Moreover, analysis of TCGA colorectal cancer data using the GEPIA2 online tool revealed that STK26 exhibits significant positive correlations with mRNA expression levels of ATF6 pathway downstream effectors (HSPA5, XBP1), clinically corroborating our experimental findings." (PMID 40869379, 2025). "Targeting the STK26-p50ATF6 axis may be a new therapy for treating colorectal cancer." (PMID 40869379, 2025). "We then verified that STK26 is a novel regulator of the 50 kDa ATF6 (p50) and prompts its stabilization by interacting with the 50 kDa ATF6 (p50), posing an important impact on the occurrence of colorectal cancer." (PMID 40869379, 2025). "The results showed that compared to those non-cancerous samples, the mRNA expression level of STK26 was significantly upregulated in colorectal cancer patients." (PMID 40869379, 2025). "Moreover, we also elucidate how STK26, highly expressed in CRC, facilitates tumorigenesis via the ATF6 signal pathway, which provides a new perspective on the role of STK26 in colorectal cancer." (PMID 40869379, 2025).
colon carcinoma (2 papers, 2021 to 2025). "To investigate STK26 expression patterns across cancers, we first analyzed the expression of STK26 in pan cancer using the TIMER2.0 online website and found that STK26 is upregulated in colon cancer." (PMID 40869379, 2025).
pituitary tumor (2 papers, 2024 to 2025). A benign or malignant neoplasm affecting the pituitary gland. "In addition, previous research has found that STK26 can promote pituitary tumor development by regulating cell proliferation and survival in a low-oxygen microenvironment, and the activation of HIF-1 and its downstream nuclear targets is also key to the role of STK26." (PMID 40869379, 2025).
adenoma (1 paper, 2022). A neoplasm arising from the epithelium. "Several of the genes encoding kinase presented isoforms, resulting from alternative splicing of mRNA: kinases PAK7 and STK26 in NR5A1-derived tumors, kinase PPIP5K2 in POU1F-derived adenomas and kinases like PPIP5K2 and kinases WEE1 and STK17 in the TBX19 tumors." (PMID 35260162, 2022).
colorectal adenocarcinoma (1 paper, 2023). The most common type of colorectal carcinoma. "MST4 (also named STK26) regulates brush border formation in colorectal adenocarcinoma cells, but the polarized localization of ZO-1 is not altered." (PMID 37155619, 2023).
lung carcinoma (1 paper, 2025). "Furthermore, a lung cancer cell model enriched in glucose was developed to facilitate the knockdown of STK26 using small interfering RNA." (PMID 40212965, 2025).
nevus (1 paper, 2019). Nevus (or naevus, plural nevi or naevi, from nævus, Latin for "birthmark") is the medical term for sharply circumscribed[1] and chronic lesions of the skin or mucosa. "Further research is needed to uncover the mechanism and role of STK26 in the transformation process of nevus into SCM." (PMID 31557882, 2019).
cancer (18 papers, 2012 to 2025). A tumor composed of atypical neoplastic, often pleomorphic cells that invade other tissues. "A univariate Cox regression analysis determined that survival outcomes were significantly affected by variables such as age, sex, cancer stage, and the level of STK26 expression." (PMID 40212965, 2025). "In this study, we discovered that RIPK2 interacts with six protein kinases: MKK7 (MAP2K7), DNA-PKcs (PRKDC), RSK2 (RPS6KA3), MST4 (STK26), MEK2 (MAP2K2), and CSK (CSK), many of which were implicated in cancer metastasis." (PMID 35115556, 2022). "In case of proteasome inhibitor MLN2238, we noted correlation of response to the drug and STK26 expression, which is a known activator of cancer progression autophagy." (PMID 33690666, 2021). "Among these genes, seven proteins (MAP2K1, FERMT2, HMGB2, FAF2, STK26, THRAP3, and KRT15) showed significant differences between carcinoma and adjacent tissues (TCGA-HNSC database)." (PMID 39319867, 2025). "To understand whether this finding is also conserved across other cancer types, we used the entire Cancer Cell Line Encyclopedia mRNA expression dataset to obtain the co-expression of all the pairwise combinations of C4orf19, PDCD10, STK24, STK25, and STK26." (PMID 38517886, 2024).
tumor (14 papers, 2015 to 2025). "The analysis employed the MCP–counter and ESTIMATE algorithms to evaluate how components of the tumor microenvironment correlate with STK26 expression." (PMID 40212965, 2025). "A tumor phonotype experiment in WT and STK26-deficient SW480 cells has enriched the function of STK26 in facilitating the growth, proliferation, and migration of tumor cells." (PMID 40869379, 2025). "In vitro, tumor phenotype assays showed that STK26 drives CRC cell growth, proliferation, and migration." (PMID 40869379, 2025). "CDK1 and STK26 were found to be the most upregulated in tumor-polarized myeloid cells." (PMID 34208043, 2021). "In a detailed examination of 114 paired samples from the TCGA–LUAD cohort, significant variations were observed in the expression of LRIF1, STK26, TNS2, and TTF2 between tumor and normal tissues, with p values less than 0.001." (PMID 40212965, 2025). "In vivo studies demonstrated that the administration of the STK26 inhibitor Hesperadin significantly suppressed CRC growth, suggesting a tumor-promoting role of STK26 in CRC pathogenesis." (PMID 40869379, 2025). "In vivo studies demonstrated that the administration of the STK26 inhibitor Hesperadin significantly suppressed CRC growth, suggesting a tumor-promoting role for STK26 in CRC pathogenesis." (PMID 40869379, 2025). "Expression levels of the key genes TNS2, LRIF1, STK26, and TTF2 showed marked differences, exhibiting substantially elevated expression in tumor tissues versus normal tissues." (PMID 40212965, 2025). "Significant change of expression, reaching 10- to 58-fold change between uterine lesion compared to non-tumor counterpart, was observed in CAPN6, CD24, HMGA1, PLAG1, SNORA48, and SNORD10 (upregulation) and DKK3 and STK26 (downregulation)." (PMID 37466765, 2024).
colorectal (1 paper, 2021). "Subsequently, we created Stk26‐Cre mice (Stk26 is the gene name of MST4) and crossed them with tdTomato mice (referred to as Stk26‐Cre;R26‐tdTomato) to genetically trace cells expressing MST4 during AOM/DSS‐induced colorectal tumorigenesis." (PMID 34240584, 2021).
STK26 also shares sentences with these, for which no sentence is quoted: hepatocellular carcinoma (5 papers); gastric cancer (3); infection (3); lymph node metastasis (3); bacterial infection (2); cerebral cavernous malformation (2); Graves disease (2); Insulin resistance (2); intracerebral hemorrhage (2); liver cancer (2); liver steatosis (2); Obesity (2); pancreatic cancer (2); Anxiety (1); atherosclerosis (1); autoimmune disease (1); Autoimmunity (1); Behavioral Disorder (1); benign prostatic hyperplasia (1); breast tumor (1); cardiomyopathy (1); cervical cancer (1); dilated cardiomyopathy (1); Glucose intolerance (1); heart failure (1); Hepatic fibrosis (1); inflammatory bowel disease (1); ischemic cardiomyopathy (1); ischemic stroke (1); liver disease (1).
A further 9 diseases each share a sentence with STK26 in 1 paper.